IGHV3-33 (immunoglobulin heavy variable 3-33)
Description:
V region of the variable domain of immunoglobulin heavy chains that participates in the antigen recognition. Immunoglobulins, also known as antibodies, are membrane-bound or secreted glycoproteins produced by B lymphocytes. In the recognition phase of humoral immunity, the membrane-bound immunoglobulins serve as receptors which, upon binding of a specific antigen, trigger the clonal expansion and differentiation of B lymphocytes into immunoglobulins-secreting plasma cells. Secreted immunoglobulins mediate the effector phase of humoral immunity, which results in the elimination of bound antigens. The antigen binding site is formed by the variable domain of one heavy chain, together with that of its associated light chain. Thus, each immunoglobulin has two antigen binding sites with remarkable affinity for a particular antigen. The variable domains are assembled by a process called V-(D)-J rearrangement and can then be subjected to somatic hypermutations which, after exposure to antigen and selection, allow affinity maturation for a particular antigen.
Synonyms: IGHV333; VH
Tractability: Antibody: its Gene Ontology location is reachable by antibodies, with high confidence; UniProt places it where antibodies can reach, with medium confidence; UniProt predicts a signal peptide or a membrane-spanning region.
Gene: Immunoglobulin variable (V) gene on chromosome 14 (106,359,793 to 106,360,324, reverse strand). Ensembl gene ENSG00000211955.
Subcellular location: Secreted; Cell membrane
Pathways (Reactome):
Immune System: Antigen activates B Cell Receptor (BCR) leading to generation of second messengers; CD22 mediated BCR regulation; Classical antibody-mediated complement activation; FCERI mediated Ca+2 mobilization; FCERI mediated MAPK activation; FCERI mediated NF-kB activation; FCGR activation; Fc epsilon receptor (FCERI) signaling; Immunoregulatory interactions between a Lymphoid and a non-Lymphoid cell; Initial triggering of complement; Regulation of Complement cascade; Regulation of actin dynamics for phagocytic cup formation; Role of LAT2/NTAL/LAB on calcium mobilization; Role of phospholipids in phagocytosis
Disease: FCGR3A-mediated IL10 synthesis; FCGR3A-mediated phagocytosis; Potential therapeutics for SARS
Hemostasis: Cell surface interactions at the vascular wall
Vesicle-mediated transport: Scavenging of heme from plasma
Gene Ontology:
Molecular function: antigen binding
Biological process: immune response; immunoglobulin mediated immune response
Cellular component: extracellular region; plasma membrane
Homologues: Paralogues in human: IGHV3-30 (98% identical), IGHV3-7 (87% identical), IGHV3-74 (87% identical), IGHV3-23 (85% identical), IGHV3-48 (85% identical), IGHV3-66 (85% identical), IGHV3-43 (84% identical), IGHV3-64 (84% identical), IGHV3OR16-13 (84% identical), IGHV3-21 (83% identical), IGHV3-53 (83% identical), IGHV3-11 (82% identical), and 65 more.